CD276 (CD276 molecule)
Diseases named in the same sentence as CD276 in open-access papers (continued):
Sharing a sentence is not in itself a finding about the gene and the disease.
carcinoma in situ (1 paper, 2024). "However, carcinoma in situ could only be detected in CD276 wKO mice after 24 weeks of carcinogen treatment." (PMID 38561369, 2024).
esophageal tumors (1 paper, 2020). "CD-276 (also known as B7-H3) showed a significantly increased expression in primary naive esophageal tumors as well." (PMID 31960110, 2020).
hepatoblastoma (1 paper, 2023). Hepatoblastoma (HB) is a malignant hepatic tumor and is the most common pediatric liver cancer. "CD276 was also highly expressed by the four hepatoblastoma cell lines analyzed." (PMID 36845728, 2023).
lymphoid leukemia (1 paper, 2025). A malignant lymphocytic neoplasm of B-cell or T-cell lineage involving primarily the bone marrow and the peripheral blood. "Additionally, CD276 mRNA was higher in LSCs compared to normal HSCs, and CD34+ cells of acute myeloid and lymphoid leukemia patients had higher CD276 protein expression than their CD34- counterparts." (PMID 40175626, 2025).
pancreatic neuroendocrine tumor (1 paper, 2025). Pancreatic endocrine tumor, also known as pancreatic neuroendocrine tumor (PNET), describes a group of endocrine tumors originating in the pancreas that are usually indolent and benign, but may have the potential to be malignant. "For example, piR‐has‐30937 derived from pancreatic neuroendocrine tumors promotes CD276 expression in macrophages via the PTEN/AKT pathway, facilitating CD276+ TAM‐mediated immunosuppression." (PMID 40761481, 2025).
Schistosoma haematobium infection (1 paper, 2025). "Machine learning emphasized SYNPO2, CD276, α2M, LCAT, and hnRNPM as the most discriminating biomarkers for Schistosoma haematobium infection." (PMID 40853910, 2025).
uveitis (1 paper, 2020). An inflammatory process affecting a part of or the entire uvea. "In addition, iPS-RPE cells also expressed B7-H3/CD276 costimulatory molecules and activated uveitis T cells through the B7-H3-TLT-2 receptor." (PMID 32899567, 2020).
tumor (1,070 papers, 2008 to 2026). "B7-H3 (CD276) stands apart from other potential targets due to its high expression in tumors cells, as well as its strong association with tumor aggressiveness and poor prognosis." (PMID 41463642, 2025). "In our study, a higher expression of the ICP molecule CD276 was shown in the tumor tissue, particularly in WLWH - IS, which was associated with increased expression of T cell exhaustion markers CTLA4 and LAG3 in different T cell subpopulations." (PMID 40393975, 2025). "This dual role in promoting both immune evasion and aggressive tumor behavior aligns with our results, where high CD276 levels associated with a suppressive immune landscape and adverse prognosis." (PMID 41488652, 2025). "Overexpression of CD276 promotes an inhibitory tumor microenvironment in HCC and is associated with poor prognosis." (PMID 40255404, 2025). "To address this issue, we have developed an Fc-optimized monoclonal antibody, 8H8_SDIE, targeting the tumor-associated antigen CD276." (PMID 40821788, 2025). "Consistent with our finding, CD276 is frequently overexpressed on various cancer cells and even on tumor-associated vasculature, while its receptor remain somewhat elusive." (PMID 41488652, 2025). "CD276 is reported to be expressed on the surface of cancer stem cells and tumor-associated macrophages, playing a critical role in suppressing the immune response against tumors." (PMID 40299539, 2025). "The CD276 protein is widely expressed in human malignancies and its overexpression in tumor tissues is associated with poor prognosis, conversely, the expression of CD276 protein is limited in normal human tissues." (PMID 38978106, 2024). "Immunohistochemistry confirmed CD276 overexpression in tumor tissues, with higher levels linked to advanced pathological grades and worse prognosis." (PMID 39319055, 2024). "Tumor-associated ECs display high expression of B7-H3 (CD276), a critical regulator of the adaptive immune response that can distinguish between physiological and pathological angiogenesis." (PMID 38426109, 2024). "CD276 has been linked with poor prognosis, aggressive clinical characteristics, and low tumor-infiltrating lymphocytes." (PMID 38566988, 2024). "B7-H3, also known as CD276, has been implicated in tumor growth, metastasis, and treatment resistance, all of which contribute to a bad prognosis for patients by assisting cancer cells in evading the surveillance by cytotoxic T cells and NK cells." (PMID 38693513, 2024). "CD276 (B7-H3), a novel immune checkpoint of the B7 family, is widely overexpressed in tumor tissues associated with a worse prognosis and provides an immunosuppression environment for diseases progression." (PMID 39872538, 2024). "CD276 is highly expressed on differentiated tumor cells as well as cancer-initiating cells, tumor-associated vasculature, and stroma." (PMID 39367484, 2024). "Taken together, CD276 is highly expressed in the vast majority of tumors and is associated with tumor progression, which indicates its potential in tumor therapy." (PMID 39766794, 2024). "Here, we show that CD276, expressed on tumor-associated macrophages (TAM), play a role in diminishing the immune response against tumors." (PMID 38561369, 2024). "CD276, which is selectively expressed in tumor and immune cells, was associated with tumor cell proliferation, metastasis, and therapeutic resistance." (PMID 39434887, 2024). "Our previous studies showed that B7-H3 (also known as CD276) is a tumor-associated antigen expressed on the surface of various cancer cell types and can be effectively targeted by B7-H3 specific CAR T cells." (PMID 38561797, 2024). "B7-H3 (CD276) is involved in the progression of HGSOC through CCL2-CCR2-tumor-associated macrophages (TAMs) axis-mediated immunosuppression." (PMID 37445830, 2023).
tumor (continued). "As a member of the CD28 and B7 families, CD276 inhibits T-cell function, and is highly expressed in numerous types of tumor, so it is often associated with poor prognosis and shorter survival rates in cancer patients." (PMID 36717836, 2023). "Elevated expression of immune-checkpoint cell surface antigen CD276 on tumor cells has been reported to be associated with poor prognosis, suggesting the suppression of anti-tumor immune responses of host T lymphocytes towards the CD276-bearing tumor cells." (PMID 38003612, 2023). "Further functional analysis of GBM showed that high expression levels of CD276 were associated with the proliferation, invasion, migration and angiogenesis of tumor cells." (PMID 36717836, 2023). "COL10A1 was positively associated with CD276, which is an immune checkpoint molecule that plays a vital role in regulating the malignant cellular-biological behaviour of tumours." (PMID 37974070, 2023). "Most clinically approved ADC payloads can be exported by drug efflux pumps such as P-glycoprotein, which are expressed on the CD276+ tumor-associated vasculature." (PMID 38019654, 2023). "CD276/B7-H3 represents a promising target for cancer therapy based on widespread overexpression in both cancer cells and tumor-associated stroma." (PMID 38019654, 2023). "SLC7A11 expression was positively associated with the expression of immune checkpoint genes (NRP1, TNFSF4, TNFRSF9, and CD276) and tumour mutation burden." (PMID 37919768, 2023). "Despite unclear underlying mechanisms, the correlation between MFAP2 and CD276 in a variety of tumors suggests that MFAP2 is a promising target for tumor immunotherapy." (PMID 35211173, 2022). "B7 homolog 3 (B7‐H3; encoded by CD276) was the only analyte to show a significant difference by race, being lower in both the tumor and stromal compartments in Black women." (PMID 34018684, 2022). "CD276, a highly glycosylated protein belonging to the immunoglobulin superfamily, has been implicated in tumor cell proliferation, migration, invasion, and angiogenesis, even acted as a dual role in the regulation of immune responses." (PMID 35752862, 2022). "In multivariable analysis, the presence of CD276 in tumor cells or diffusely within tumor vasculature was significantly associated with an increased risk of death from ccRCC." (PMID 33842369, 2021). "When analyzing the association between CD276 expression and tumor stage by immunohistochemistry in sample subsets, the highest median scores were observed in T2b and T3a tumors, followed by a minor, non-significant decline in higher stages (T3b and T4)." (PMID 33845814, 2021). "Anti-CD276-drug conjugate has been described as capable to selectively attack both the tumor and tumor-associated vessels." (PMID 33921099, 2021). "We observed increased expression of 5 immune suppressive genes including PVR (CD155), TGFB1, NT5E (CD73), VEGFA, and CD276 (B7-H3) in 9p21-loss tumors across multiple tumor types/subtypes when compared to 9p21-WT tumors." (PMID 34556668, 2021). "It has been shown that CD276 can promote tumor proliferation, angiogenesis, and metastasis, and is associated with shorter survival time in multiple tumor types." (PMID 34073720, 2021). "In conclusion, our data suggest that tumor-expressed CD276 is involved in regulating the recruitment of tumor-associated macrophages and provide insights, for the first time, in signaling mediated by CD276 in macrophages." (PMID 34290311, 2021). "Another target with great translational potential is CD276 (or B7-H3), a checkpoint molecule expressed in most cancer cells and tumor-associated vascular cells in ACC." (PMID 33918733, 2021). "CD276 is also associated with a lower number of tumor-infiltrating lymphocytes, implying a role for CD276 in tumor immune evasion and inhibition of T cell antitumor immunit y." (PMID 35052695, 2021). "Tumor cells express low levels of CD276, but tumor associated endothelial cells express high levels." (PMID 31948091, 2020).
tumor (continued). "Positive expression of CD276 was detected on the cell membrane and in the cytoplasm of cancer cells or tumor-associated vascular cells in 91.67% (44/48) of ACCs." (PMID 31998416, 2020). "We demonstrated that differential expression patterns of CD276 were closely associated with tumor progression and prognosis in ACC patients." (PMID 31998416, 2020). "High CD276 expression is associated with increased tumor size, lymphovascular invasion, poorly differentiated tumors, and shorter overall patient survival." (PMID 33033253, 2020). "CD276 expression is also associated with tumor-infiltrating FOXP3 + regulatory T cells which inhibit effector T cells and is important for immune evasion and tumorigenesis in prostate cancer." (PMID 33033253, 2020). "In another study, high CD276 expression was observed to be associated with high tumor grade and short overall survival, possibly in synergy with Treg cells, allowing tumors to evade immune responses." (PMID 31737785, 2019). "Furthermore, PYGB expression was positively associated with CD276 (also known as B7-H3), an immune checkpoint molecule implicated in the inhibition of anti-tumor T-cell responses." (PMID 40458414, 2025). "In addition, high CD276 expression is associated with poorer prognosis in various cancer entities, e.g. higher tumor grade, shorter OS, and a lower presence of tumor-infiltrating lymphocytes." (PMID 40707958, 2025). "Similar to PD-L1, CD276 prevents the surveillance of tumor cells by cytotoxic T and NK-cells and its expression on BC cells has been reported to associate with poor prognosis, enlarged tumor size, lymph node migration and cancer recurrence." (PMID 40452017, 2025). "CD276 expression is associated with poor prognosis, likely due to its role in inhibiting the activity of T cells and NK cells, thereby providing a rationale for targeting this antigen in therapeutic strategies aimed at enhancing anti-tumor immunity." (PMID 40821788, 2025). "Furthermore, multivariate COX analysis indicated that tumor diameter and CD276 expression levels were independent risk factors for postoperative PFI in patients with ccRCC (p < 0.05)." (PMID 39210603, 2024). "Additionally, we observed a direct association between tumor stage advancement and increased CD276 expression (p<0.05)." (PMID 39319055, 2024). "Furthermore, COX multivariate analysis revealed that tumor diameter and CD276 expression levels were independent risk factors influencing PFI (p < 0.05)." (PMID 39210603, 2024). "Interestingly, a tumor-associated antigen CD276/B7-H3 mRNA expression also showed a significant (p < 0.0001) 4.03-fold increase in tumor tissue, providing further insights into the roles of macrophages and tumor cells in the immunosuppressive TME." (PMID 38539537, 2024). "Interestingly, the mRNA expression of a tumor-associated antigen, CD276/B7-H3, showed a significant (p < 0.0001) 4.03-fold increase in tumor tissue, giving further insights into the roles of macrophages and tumor cells in supporting the immunosuppressive TME." (PMID 38539537, 2024). "Interestingly, a tumor-associated antigen CD276/B7-H3 mRNA expression increased in tumor tissue, giving further insights into the roles of macrophages and tumor cells in the immunosuppressive TME." (PMID 38539537, 2024). "Moreover, high expression of CD276 is associated with poor function of tumor-infiltrating T cells in OC." (PMID 38970121, 2024). "The high expression of CD276 was associated with tumor progression, leading to poor survival." (PMID 39766794, 2024). "However, CD276 was expressed highly in the high-risk population, suggesting that immune checkpoints were involved in tumor progression and are promising applications in the low-risk population to help guide immunotherapy." (PMID 37680641, 2023).
tumor (continued). "In this study, only ES4-WT tumors on the right flank could be completely eradicated by the ADC, while the ES4-KO tumors on the left flank exhibited a partial response, presumably due to ADC targeting of CD276+ tumor-associated stromal cells." (PMID 38019654, 2023). "In addition, analysis of cumulative survival time and recurrence revealed that samples with CD276-positive tumor vasculature are associated with a significantly shorter survival time and a higher rate of recurrence." (PMID 37373167, 2023). "Moreover, SLC25A1 was positively associated with MSI, TMB, and CD276 and tightly correlated with tumor-infiltrating immune cells." (PMID 37981593, 2023). "At present, the molecular mechanism underlying CD276 expression regulation is becoming increasingly well understood, as it has been shown to promote tumor activity and to enhance cell proliferation, migration, invasion, angiogenesis and chemotherapy resistance both in vivo and in vitro." (PMID 36717836, 2023). "CD276 was a novel immune checkpoint molecular implicated in tumor immune escape." (PMID 36175880, 2022). "A follow-up study by the same group, furthermore observed that tumor-associated endothelial vessels contain specialized endothelial cells, high in CD276 and PLVAP as biomarkers, that are the main drivers for transporting NPs from the bloodstream into the tumor microenvironment." (PMID 36135572, 2022). "Moreover, CD276 enhanced the angiogenic function of tumor-associated macrophages, and CD276-blocking antibody raised the therapeutic efficiency of paclitaxel /anti-PD-1 in 4T1 tumor-bearing mice." (PMID 35784750, 2022). "CD276-expressing tumors were associated with the exclusion of CD8+ tumor-infiltrating lymphocytes." (PMID 36685583, 2022). "Positive expression of CD276 in the tumor vasculature may also indicate a higher risk of local tumor infiltration, adjacent organ invasion or venous tumor thrombus (P = 0.029), and advanced ENSAT stage (P = 0.020)." (PMID 31998416, 2020). "Given the high recurrence rate of ACC, we next assessed whether CD276 expression is associated with tumor recurrence after surgical resection." (PMID 31998416, 2020). "For example, CDCA2, CDCA3, and CDCA8 exhibited moderate positive correlations with the immune checkpoint CD276, suggesting that higher CDCA expression might be associated with increased levels of CD276, potentially aiding immune evasion in the tumor microenvironment." (PMID 40114265, 2025). "Therefore, CD276 is highly expressed in tumor tissues and is associated with tumor progression." (PMID 39766794, 2024). "Importantly, CD276 expressed by tumour cells may affect the differentiation of tumour-associated macrophages, and CD276 is also expressed by at least some macrophages in GBM tissue." (PMID 35884502, 2022). "Furthermore, higher intensity of CD276 in tumor cells correlated with increased recurrence risk and overall worse prognosis, while at the same time, increased expression of CD276 in tumor vasculature was associated with tumor invasion of adjacent structures and more advanced disease stage." (PMID 33918733, 2021). "Indeed, even though CD276 displays a widespread expression pattern in mouse and human tissues, the fact that it is so highly expressed by tumour cells and the associated tumour vasculature, resulted in ADCs against CD276 only having substantial effects upon the tumour microenvironment." (PMID 31287944, 2019). "B7-H3 (also known as CD276) is a type 1 transmembrane glycoprotein that acts as a co-inhibitory molecule in the tumor microenvironment (TME) by impairing T-cell activation." (PMID 41562777, 2026). "In particular, the FGFR4.28HTM.28z-CD276.8HTM.BBz BiCisCAR T cells have demonstrated faster tumor clearance, higher persistence, and lower expression of exhaustion markers in RMS models." (PMID 41328353, 2026).